IGKV2D-40 (immunoglobulin kappa variable 2D-40)
Description:
V region of the variable domain of immunoglobulin light chains that participates in the antigen recognition. Immunoglobulins, also known as antibodies, are membrane-bound or secreted glycoproteins produced by B lymphocytes. In the recognition phase of humoral immunity, the membrane-bound immunoglobulins serve as receptors which, upon binding of a specific antigen, trigger the clonal expansion and differentiation of B lymphocytes into immunoglobulins-secreting plasma cells. Secreted immunoglobulins mediate the effector phase of humoral immunity, which results in the elimination of bound antigens. The antigen binding site is formed by the variable domain of one heavy chain, together with that of its associated light chain. Thus, each immunoglobulin has two antigen binding sites with remarkable affinity for a particular antigen. The variable domains are assembled by a process called V-(D)-J rearrangement and can then be subjected to somatic hypermutations which, after exposure to antigen and selection, allow affinity maturation for a particular antigen.
Synonyms: IGKV2D40; O1
Tractability: Antibody: UniProt places it where antibodies can reach, with medium confidence; UniProt predicts a signal peptide or a membrane-spanning region; its Gene Ontology location is reachable by antibodies, with medium confidence.
Gene: Immunoglobulin variable (V) gene on chromosome 2 (89,851,758 to 89,852,493, forward strand). Ensembl gene ENSG00000251039.
Subcellular location: Secreted; Cell membrane
Pathways (Reactome):
Immune System: Antigen activates B Cell Receptor (BCR) leading to generation of second messengers; CD22 mediated BCR regulation; Classical antibody-mediated complement activation; FCERI mediated Ca+2 mobilization; FCERI mediated MAPK activation; FCERI mediated NF-kB activation; FCGR activation; Fc epsilon receptor (FCERI) signaling; Immunoregulatory interactions between a Lymphoid and a non-Lymphoid cell; Initial triggering of complement; Regulation of Complement cascade; Regulation of actin dynamics for phagocytic cup formation; Role of LAT2/NTAL/LAB on calcium mobilization; Role of phospholipids in phagocytosis
Disease: FCGR3A-mediated IL10 synthesis; FCGR3A-mediated phagocytosis; Potential therapeutics for SARS
Hemostasis: Cell surface interactions at the vascular wall
Vesicle-mediated transport: Scavenging of heme from plasma
Gene Ontology:
Molecular function: antigen binding
Biological process: immune response
Cellular component: blood microparticle; extracellular exosome; extracellular region; immunoglobulin complex; plasma membrane
Homologues: Orthologues: mouse Igkv2-109 (76% identical). Paralogues in human: IGKV2-28 (88% identical), IGKV2D-28 (88% identical), IGKV2-40 (86% identical), IGKV2D-29 (86% identical), IGKV2-24 (82% identical), IGKV2-30 (82% identical), IGKV2D-30 (81% identical), IGKV2D-24 (80% identical), IGKV2D-26 (79% identical), IGKV3-20 (60% identical), IGKV3-11 (59% identical), IGKV3D-20 (59% identical), and 81 more.
Diseases named in the same sentence as IGKV2D-40 in open-access papers:
IGKV2D-40 is named in the same sentence as 9 diseases in open-access papers, as found by Europe PMC text mining. Sharing a sentence is not in itself a finding about the gene and the disease.
IGKV2D-40 shares sentences with these, for which no sentence is quoted: infection (8 papers); tumor (3); cholera (2); glioblastoma (1); glioma (1); hepatocellular carcinoma (1); Liver abscess (1); ovarian carcinoma (1); ZIKV infection (1).